PTPRB (protein tyrosine phosphatase receptor type B)
Description:
Plays an important role in blood vessel remodeling and angiogenesis. Not necessary for the initial formation of blood vessels, but is essential for their maintenance and remodeling. Can induce dephosphorylation of TEK/TIE2, CDH5/VE-cadherin and KDR/VEGFR-2. Regulates angiopoietin-TIE2 signaling in endothelial cells. Acts as a negative regulator of TIE2, and controls TIE2 driven endothelial cell proliferation, which in turn affects blood vessel remodeling during embryonic development and determines blood vessel size during perinatal growth. Essential for the maintenance of endothelial cell contact integrity and for the adhesive function of VE-cadherin in endothelial cells and this requires the presence of plakoglobin (By similarity).
Synonyms: R-PTP-beta; PTPB; HPTP-BETA; HPTPB; VEPTP
Tractability: Small molecule: a drug acting on it is in phase 2 or 3 trials; a structure with a bound ligand is known; a high-quality ligand is known; it has a binding pocket of medium quality; it belongs to a druggable protein family. Antibody: its Gene Ontology location is reachable by antibodies, with high confidence; UniProt predicts a signal peptide or a membrane-spanning region; the Human Protein Atlas places it where antibodies can reach. PROTAC: ubiquitination databases record sites on it; a small molecule that binds it is known.
Target class: Enzyme; Protein Phosphatase; Receptor tyrosine-protein phosphatase; Tyrosine protein phosphatase; Phosphatase
Gene: Protein-coding gene on chromosome 12 (70,515,870 to 70,637,440, reverse strand). Ensembl gene ENSG00000127329.
Subcellular location: Membrane
Subcellular location (Human Protein Atlas): Plasma membrane; Cell Junctions; Vesicles
Pathways (Reactome):
Immune System: Neutrophil degranulation
Gene Ontology:
Molecular function: cadherin binding; protein binding; transmembrane receptor protein tyrosine kinase inhibitor activity; transmembrane receptor protein tyrosine phosphatase activity; protein tyrosine phosphatase activity
Biological process: angiogenesis; dephosphorylation; osteoblast differentiation; phosphate-containing compound metabolic process; protein dephosphorylation; glial cell migration
Cellular component: receptor complex; plasma membrane; specific granule membrane; tertiary granule membrane; membrane
Genetic constraint (gnomAD): Loss-of-function variants: 90 observed, 230.28 expected, observed/expected ratio (o/e) 0.39, 90% interval 0.33 to 0.47. The upper end of that interval is the gene's LOEUF score, 0.47, which puts it in group 2 of 6, group 1 being the genes least tolerant of losing a copy. Missense variants: 2,239 observed, 2,708.9 expected, observed/expected ratio (o/e) 0.83, 90% interval 0.8 to 0.86. Synonymous variants: 940 observed, 1,016.4 expected, observed/expected ratio (o/e) 0.92, 90% interval 0.88 to 0.98.
Cancer hallmarks: suppression of growth (promotes); angiogenesis (promotes); invasion and metastasis (suppresses); tumour promoting inflammation (promotes); invasion and metastasis (promotes); angiogenesis (suppresses)
Homologues: Orthologues: chimpanzee PTPRB (99% identical), macaque PTPRB (97% identical), rabbit PTPRB (89% identical), pig PTPRB (88% identical), dog PTPRB (88% identical), guinea pig PTPRB (86% identical), rat Ptprb (83% identical), mouse Ptprb (77% identical), tropical clawed frog ptprb (62% identical), zebrafish ptprb (38% identical). Paralogues in human: PTPRJ (16% identical), PTPN13 (15% identical), PTPRS (15% identical), PTPRF (14% identical), PTPRD (14% identical), PTPRH (13% identical), PTPRT (12% identical), PTPRM (12% identical), PTPRO (12% identical), PTPRK (12% identical), PTPRU (12% identical), PTPRZ1 (12% identical), and 23 more.
Diseases named in the same sentence as PTPRB in open-access papers:
PTPRB is named in the same sentence as 76 diseases in open-access papers, as found by Europe PMC text mining. Sharing a sentence is not in itself a finding about the gene and the disease. The quoted sentences say what the papers report.
angiosarcoma (18 papers, 2015 to 2025). A malignant tumor arising from the endothelial cells of the blood vessels. "PTPRB mutations are considered rare in solid malignancies, nevertheless they were present in 26% of 39 angiosarcoma tumors sequenced." (PMID 31089155, 2019). "PTPRB is a negative regulator of angiogenesis and is frequently mutated in angiosarcoma." (PMID 34885197, 2021). "ENMD-2076 evaluation in PTPRB mutated tumors and/or angiosarcoma is warranted." (PMID 31089155, 2019). "Recently another PTP, PTPRB, was found to be mutated in 26% of angiosarcomas." (PMID 29872503, 2018). "More recently, whole exome sequencing of primary and secondary angiosarcoma demonstrated mutations in the endothelial phosphatase, Protein tyrosine phosphatase, receptor type, B (PTPRB) and Phospholipase C, gamma 1 (PLCG1), a signal transducer of tyrosine kinase activators." (PMID 28056866, 2017). "The description of PTPRB mutations in angiosarcoma not only reconfirms the importance of RTK signaling in this tumor, but also raises the possibility that a broader range of RTKs expressed (or misexpressed) in endothelial cells may be derepressed and contribute to oncogenesis." (PMID 29872503, 2018). "On the other hand, it has been shown that inactivating genetic mutations in the endothelial phosphatase PTPRB, another negative regulator of VEGFR-2 signaling, occur in about 26% of malign vascular tumors, named angiosarcomas." (PMID 33078209, 2021). "Recent studies demonstrated that the PTPRB and PLCG1 genes involved in angiogenesis were mutated in angiosarcomas." (PMID 33509230, 2021). "Recently, a genome sequencing effort discovered recurrent mutations in PTPRB, a vascular endothelial cell-specific protein tyrosine phosphatase (PTP) that regulates receptor tyrosine kinases (RTKs), in angiosarcoma." (PMID 29872503, 2018). "We identified a number of known genetic alterations in angiosarcomas, including MYC and KLT4 amplifications, RAS mutations, inactivating PTPRB mutations and an activating PLCG1 mutation." (PMID 26440310, 2015). "Interestingly, primary cutaneous angiosarcomas are also associated with mutations in fusion genes like NUP160-SCL43A3 and PTPRB/VE-PTP." (PMID 38826780, 2024). "Previous studies on the genomic landscape of angiosarcoma have described recurrent somatic mutations of angiogenic signaling pathway genes, including KDR, PTPRB, and PLCG114–18, as well as genes involved in oncogenic signaling pathways such as MAPK, PIK3CA/AKT/mTOR, and TP5319,20." (PMID 37106027, 2023). "Recurrent driver mutations have been identified in the PTPRB or PLCG1 gene in 38% angiosarcoma patients, including primary and secondary tumors, which reinforce therapeutic efforts to target angiogenesis signaling in angiosarcoma." (PMID 27531900, 2016). "The pathogenesis of angiosarcoma is probably also related to other genes, including CIC gene rearrangement, increased expression of the MYC gene and FLT-4 gene, and mutations of PTPRB and PLCG1, but the present study focused on the PD-1/PD-L1 and PI3K/mTOR signaling pathways." (PMID 34397726, 2021). "However, the substrates of PTPRB in endothelial progenitor cells have not been elucidated nor have they been studied in the context of angiosarcoma." (PMID 29872503, 2018).
glaucoma (7 papers, 2019 to 2025). Increased pressure in the eyeball due to obstruction of the outflow of aqueous humor. "According to a study, in glaucoma models, blocking PTPRB can stop retinal ganglion cell layer destruction." (PMID 41196918, 2025). "Twelve of these genes, including PTPRB, HFM1, TAF1B, AAK1, FOXD1, EHMT1, and DNTT, are associated with glaucoma topical treatments (P < 1 × 10−5)." (PMID 36450729, 2022). "Several of these ExWAS significant IOP genes, such as PTPRB, KIF21A, DNTT, also show a significant association with glaucoma in UKB with P = 3.26 × 10−5, 0.009, 0.007, respectively." (PMID 36450729, 2022). "As an alternative to ANGPT1-mimetics, inhibition or genetic deletion of PTPRB (VE-PTP), which negatively regulates the TEK receptor, has been studied in animal models and is currently being tested in adult patients with glaucoma." (PMID 34663817, 2021).
colorectal cancer (5 papers, 2017 to 2025). A primary or metastatic malignant neoplasm that affects the colon or rectum. "Beyond its role in angiogenesis, PTPRB has been implicated in promoting metastasis of colorectal carcinoma by inducing epithelial-mesenchymal transition." (PMID 40666093, 2025). "In colorectal carcinoma, PTPRB was shown to be highly expressed and promote metastasis of tumor cells via inducing EMT." (PMID 34516350, 2021). "Here we show that PTPRB promotes metastasis of colorectal cancer (CRC) cells via inducing epithelial-mesenchymal transition (EMT)." (PMID 31040266, 2019). "For instance, a model of seven-gene signatures (NHLRC3, ZDHHC21, PRR14L, CCBL1, PTPRB, PNPO and PPIP5K2) was applied to predict OS by dividing colorectal cancer (CRC) patients into low-risk and high-risk groups." (PMID 28827775, 2017). "However, in colorectal carcinoma, PTPRB displayed an anti-oncogene effect, suggesting its multiple functions in different types of tumors." (PMID 34516350, 2021).
melanoma (5 papers, 2014 to 2026). A malignant, usually aggressive tumor composed of atypical, neoplastic melanocytes. "These melanoma-private mutations occurred in genes linked to chromatin regulation (ARID1A and ARID2), cell growth (e.g., PIK3CA), cell adhesion (e.g., EPHA2), splicing (SF3B1), angiogenesis (PTPRB), and classic tumor suppressors (NOTCH3, CDKN2A, and PTEN)." (PMID 41516405, 2026).
diabetic macular edema (4 papers, 2017 to 2024). "PTPRB inhibition has been previously studied as a potential therapeutic intervention in vascular disease, and the PTPRB inhibitor AKB-9778 is currently undergoing clinical trials for treatment of diabetic macular edema, where it is well-tolerated by patients." (PMID 31621585, 2019).
ischemic stroke (3 papers, 2016 to 2022). A stroke disorder caused by obstruction of blood flow to the brain, due to thrombotic (local blood clot formation) or embolic (due to a blood clot or other material traveling from another site) event. "For example, the molecular target of hsa-miR-676-3p, SMURF2, is involved in neurodifferentiation in recovery phase following ischemic stroke, while its other targets, PTPRB and ANP32B, have also been previously investigated in experimental stroke models." (PMID 35328807, 2022).
lung carcinoma (3 papers, 2021 to 2022). "For instance, overexpression of PTPRB suppressed the growth and migration of bronchogenic carcinoma cells via increasing Src phosphorylation, and predicted a poor prognosis of patients with lung cancer." (PMID 34516350, 2021). "Our data revealed PTPRB as a tumor promoter, which was not in line with its effects on lung cancer and osteosarcoma." (PMID 34516350, 2021).
Stroke (3 papers, 2016 to 2022). Sudden impairment of blood flow to a part of the brain due to occlusion or rupture of an artery to the brain. "Notably, PTPRB encodes the protein tyrosine phosphatase receptor type B (also known as vascular endothelial protein tyrosine phosphatase—VE-PTP), which is involved in the maintenance of vascular integrity and is a potential therapeutic target for vascular diseases, including stroke." (PMID 35328807, 2022).
diabetic retinopathy (2 papers, 2018 to 2023). "TIE2 appears to be an especially sensitive substrate in mature endothelium as targeted inhibition of PTPRB was demonstrated to activate receptor signaling and to reduce neovascularization associated with macular degeneration and diabetic retinopathy." (PMID 29872503, 2018).
injury (2 papers, 2019 to 2022). Damage inflicted on the body as the direct or indirect result of an external force, with or without disruption of structural continuity. "HIF-2α upregulation was shown to be protective in a lung injury mouse model as it promotes endothelial barrier maintenance through regulation of a vascular phosphotyrosine phosphatase (VE-PTP or PTPRB) which promotes endothelial cadherin junction maintenance." (PMID 31380363, 2019).
myocardial infarction (2 papers, 2018 to 2019). Gross necrosis of the myocardium, as a result of interruption of the blood supply to the area, as in coronary thrombosis. "By comparing the co-expression with ceRNA networks, five lncRNAs (SNHG9, LINC02202, UBAC2-AS1, PTCSC3 and myocardial infarction associated transcript (MIAT)) and 32 genes (such as PIK3R1, PTPRB) were found to be shared." (PMID 31534842, 2019).
non-small cell lung carcinoma (2 papers, 2019 to 2021). A group of at least three distinct histological types of lung cancer, including non-small cell squamous cell carcinoma, adenocarcinoma, and large cell carcinoma. "PTPRB was reported to be downregulated in non-small cell lung cancer tissues and serves as an independent biomarker for a patient’s prognosis." (PMID 31829261, 2019). "For LUAD, PTPRB is the only identified gene and is found to be mutually exclusive with EGFR, a well-known oncogene in non-small cell lung cancer." (PMID 34899838, 2021).
osteosarcoma (2 papers, 2019 to 2021). A usually aggressive malignant bone-forming mesenchymal neoplasm, predominantly affecting adolescents and young adults. "In conclusion, we demonstrated the tumor-promoting role of miR-624-5p in osteosarcoma progression and its underlying mechanism through PTPRB and the Hippo pathway." (PMID 31829261, 2019).
sarcoma (2 papers, 2018 to 2019). A usually aggressive malignant neoplasm of the soft tissue or bone.
acral melanoma (1 paper, 2022). "Also, it has been reported that subungual melanoma harbors more distinct genomic alterations including CARD11, ARID2, ARID1A, ARID1B, PTPRB, and PTPRK genes, compared with acral melanoma." (PMID 35484605, 2022).
alcoholism (1 paper, 2018). "To date, only a single study implicated PTPRB in substance abuse, finding significant associations for two PTPRB polymorphisms with alcoholism vulnerability in unrelated European-American individuals." (PMID 29675039, 2018).
bipolar affective disorder (1 paper, 2022). "Until now, only the rs2492367 polymorphism in DISC1 has been shown to be associated with the bipolar affective disorder; there were no reports about the other SNPs of PTPRB, TRAF3IP3, and DISC1 genes that can affect protein function and disease." (PMID 36397361, 2022).
bronchogenic carcinoma (1 paper, 2021). A lung carcinoma arising from the bronchial epithelium. "For instance, PTPRB was shown to reduce the potential ability of the growth and invasion of bronchogenic carcinoma cells through modulating the phosphorylation of the proto-oncogene tyrosine-protein kinase Src." (PMID 34516350, 2021).
carcinoid (1 paper, 2014). "We also evaluated the expression data of CREB5, PTPRB and COL4A3 from Oncomine, indicating that CREB5, PTPRB and COL4A3 were significantly lower in carcinoid than normal lung tissues, which was accordant to the results of the DASL and RNA-seq datasets." (PMID 25105010, 2014).
cervical squamous cell carcinoma (1 paper, 2021). A squamous cell carcinoma arising from the cervical epithelium. "Aberrant PTPRB expression in CC and survival outcomes were constructed using The Cancer Genome Atlas (TCGA) database and tissue microarray cervical squamous cell carcinoma cohort." (PMID 34516350, 2021).
Cluster headache (1 paper, 2014). A type of headache characterized by repeated attacks of unilateral pain lasting 15 to 180 minutes and associated with local autonomic signs. "PTPRB has been reported to be a drug addiction-associated gene, and CREB5 to be upregulated in the blood of cases with cluster headaches when compared to controls." (PMID 25105010, 2014).
colon cancer (1 paper, 2022). "Recent studies have shown that PTPRB promotes colon cancer invasion and metastasis by inducing EMT, and PTPRB is a potential therapeutic target for colon cancer." (PMID 36581992, 2022).
COVID-19 (1 paper, 2021). A disease caused by infection with severe acute respiratory syndrome coronavirus 2. "Plasma from patients with severe COVID-19 did not significantly alter TIE2 or PTPRB (the gene encoding VE-PTP) expression." (PMID 34506304, 2021).
liposarcoma (1 paper, 2024). A usually painless malignant tumor that arises from adipose tissue. "The two tumor samples (primary tumor and recurrence) of one patient (cases 8a and 8b) both demonstrated PTPRB and MDM2 amplification (these cases were reevaluated to rule out liposarcoma; see Section 3)." (PMID 38791144, 2024).
lymph node metastasis (1 paper, 2020). "A clonal driver mutation in MYCN (MIM: 164840; CRC-190), and subclonal driver mutations in ELF4 (MIM: 300775; 083-03), PTPRB (MIM: 176882; CRC-233 lymph node metastasis), FUS (MIM: 137070), and ERCC4 (MIM: 133520) in CRC-449 were all specific to metastatic tumours." (PMID 33053768, 2020).
meningitis (1 paper, 2020). A disorder characterized by acute inflammation of the meninges of the brain and/or spinal cord. "In the current meningitis data set, we observe an increase in angiopoietin 2 (Ang-2) and a decrease in Tie2 as well as protein tyrosine phosphatase receptor type B (PTPRB; one of the top down-regulated genes)." (PMID 32529267, 2020).
myeloid sarcoma (1 paper, 2023). A tumor mass composed of myeloblasts or immature myeloid cells. "Further analysis of the sequencing results revealed missense mutations in the FLT3 and PTPRB genes, which are associated with myeloid sarcoma." (PMID 36871023, 2023).
myopia (1 paper, 2008). "Based on these results, we speculate that the relative downregulation of PTPRB in the choroids of minus lens-treated eyes may represent a response by choroidal vascular endothelial cells to regulate choroidal vascularization during the development of myopia." (PMID 18698376, 2008).
pulmonary carcinoid tumor (1 paper, 2019). "It was also found that higher expressions of PTPRB predict favorable survival rates among pulmonary carcinoid tumor patients." (PMID 31829261, 2019).
pulmonary fibrosis (1 paper, 2025). Chronic progressive interstitial lung disorder characterized by the replacement of the lung tissue by connective tissue, leading to progressive dyspnea, respiratory failure, or right heart failure. "It has been shown to regulate pulmonary fibrosis by inhibiting endothelial-to-mesenchymal transition and lung fibroblast proliferation via the PTPRB signaling pathway." (PMID 40148559, 2025).
skin cutaneous melanoma (1 paper, 2022). "Several PTPs, like PTPRT, PTPRB, and PTPRD, demonstrated a high mutation rate in skin cutaneous melanoma (SKCM) and uterine corpus endometrial carcinoma (UCEC) compared with other cancers due to the higher global mutation burden in the two cancer types." (PMID 36341348, 2022).
squamous cell carcinoma (1 paper, 2017). A carcinoma arising from squamous epithelial cells. "Subsequently, down-regulated genes (FAS, PTPRB, MEOX2 and RECK) were considered where lower expression of the genes correlated with poor prognosis in lung adeno- but not so in squamous cell carcinoma patients." (PMID 29254206, 2017).
thyroid autoimmune (1 paper, 2021). "Therefore, further studies are necessary to figure out whether the variations of PTPRB, PIK3R3 and TRAF3IP3 are involved in the dysfunction of thyroid autoimmune." (PMID 33568133, 2021).